CACNG7 (calcium voltage-gated channel auxiliary subunit gamma 7)
Description:
Regulates the activity of L-type calcium channels that contain CACNA1C as pore-forming subunit. Regulates the trafficking and gating properties of AMPA-selective glutamate receptors (AMPARs). Promotes their targeting to the cell membrane and synapses and modulates their gating properties by slowing their rates of activation, deactivation and desensitization and by mediating their resensitization. Displays subunit-specific AMPA receptor regulation. Shows specificity only for GRIA1 and GRIA2.
Tractability: Small molecule: an approved drug acts on it; a high-quality ligand is known; it belongs to a druggable protein family. Antibody: UniProt places it where antibodies can reach, with high confidence; its Gene Ontology location is reachable by antibodies, with high confidence; UniProt predicts a signal peptide or a membrane-spanning region.
Gene: Protein-coding gene on chromosome 19 (53,909,278 to 53,943,950, forward strand). Ensembl gene ENSG00000105605.
Subcellular location: Cell membrane
Pathways (Reactome):
Muscle contraction: Phase 0 - rapid depolarisation; Phase 2 - plateau phase
Cellular responses to stimuli: Mechanical load activates signaling by PIEZO1 and integrins in osteocytes
Gene Ontology:
Molecular function: calcium channel regulator activity; protein binding; channel regulator activity; voltage-gated calcium channel activity
Biological process: regulation of AMPA receptor activity; calcium ion transport; positive regulation of synaptic transmission, glutamatergic; postsynaptic neurotransmitter receptor diffusion trapping; transmission of nerve impulse; calcium ion transmembrane transport; neurotransmitter receptor localization to postsynaptic specialization membrane; positive regulation of dendrite extension; regulation of mRNA stability
Cellular component: L-type voltage-gated calcium channel complex; AMPA glutamate receptor complex; plasma membrane; postsynaptic density membrane; voltage-gated calcium channel complex; cerebellar mossy fiber; early endosome; glutamatergic synapse; membrane; neuronal cell body
Genetic constraint (gnomAD): Loss-of-function variants: 9 observed, 27.28 expected, observed/expected ratio (o/e) 0.33, 90% interval 0.2 to 0.58. The upper end of that interval is the gene's LOEUF score, 0.58, which puts it in group 2 of 6, group 1 being the genes least tolerant of losing a copy. Missense variants: 297 observed, 401.41 expected, observed/expected ratio (o/e) 0.74, 90% interval 0.67 to 0.81. Synonymous variants: 170 observed, 166.86 expected, observed/expected ratio (o/e) 1.02, 90% interval 0.9 to 1.16.
Homologues: Orthologues: chimpanzee CACNG7 (100% identical), guinea pig CACNG7 (100% identical), macaque CACNG7 (100% identical), mouse Cacng7 (100% identical), pig CACNG7 (100% identical), rat Cacng7 (100% identical), rabbit CACNG7 (99% identical), tropical clawed frog cacng7 (93% identical), zebrafish cacng7a (82% identical), zebrafish cacng7b (81% identical), dog CACNG7 (63% identical), Drosophila melanogaster stg1 (32% identical), and 1 more. Paralogues in human: CACNG5 (69% identical), CACNG2 (33% identical), CACNG3 (32% identical), CACNG8 (31% identical), CACNG4 (31% identical).
Diseases named in the same sentence as CACNG7 in open-access papers:
CACNG7 is named in the same sentence as 10 diseases in open-access papers, as found by Europe PMC text mining. Sharing a sentence is not in itself a finding about the gene and the disease. The quoted sentences say what the papers report.
brain tumor (1 paper, 2021). "Only broad modified gene expression of CACNG7 has been described in brain tumor compared with normal human fetal neural stem cells." (PMID 34685551, 2021).
Cognitive impairment (1 paper, 2019). Abnormal cognition is characterized by deficits in thinking, reasoning, or remembering. "Among the significantly enriched signaling pathways from KEGG analysis, oxytocin signaling pathway (PATH:04921; Cacng2, Adcy1, Kcnj4, Kcnj9, Adcy8, Pik3cd, Elk1, Adcy4, Camkk2, Cacng7, Nos3, Kcnj2) may play an important role in the sevoflurane-induced cognitive impairment." (PMID 31582589, 2019).
epilepsy (1 paper, 2025). A brain disorder characterized by episodes of abnormally increased neuronal discharge resulting in transient episodes of sensory or motor neurological dysfunction, or psychic dysfunction. "In addition, no pathogenic variants exclusively associated with epilepsy or seizures have been identified for CACNG7 and CACNG8." (PMID 40313715, 2025).
Intellectual disability (1 paper, 2022). "CACNG7 has an important role in neural pathways associated with non-syndromic intellectual disability." (PMID 35958988, 2022).
CACNG7 also shares sentences with these, for which no sentence is quoted: arrhythmogenic right ventricular cardiomyopathy (1 paper); dilated cardiomyopathy (1); fragile X syndrome (1); hypertrophic cardiomyopathy (1); schizophrenia (1); spinocerebellar ataxia type 23 (1).